SASH1 (SAM and SH3 domain containing 1)
Description:
Is a positive regulator of NF-kappa-B signaling downstream of TLR4 activation. It acts as a scaffold molecule to assemble a molecular complex that includes TRAF6, MAP3K7, CHUK and IKBKB, thereby facilitating NF-kappa-B signaling activation. Regulates TRAF6 and MAP3K7 ubiquitination. Involved in the regulation of cell mobility. Regulates lipolysaccharide (LPS)-induced endothelial cell migration. Is involved in the regulation of skin pigmentation through the control of melanocyte migration in the epidermis.
Synonyms: KIAA0790; dJ323M4.1; SH3D6A; CAPOK; DUH; DUH1
Tractability: PROTAC: ubiquitination databases record sites on it.
Gene: Protein-coding gene on chromosome 6 (148,272,304 to 148,552,044, forward strand). Ensembl gene ENSG00000111961.
Subcellular location: Cytoplasm
Subcellular location (Human Protein Atlas): Cytosol; Nucleoplasm
Gene Ontology:
Molecular function: G-protein alpha-subunit binding; mitogen-activated protein kinase kinase kinase binding; molecular adaptor activity; protein binding; protein kinase binding
Biological process: positive regulation of angiogenesis; positive regulation of endothelial cell migration; positive regulation of JUN kinase activity; positive regulation of lipopolysaccharide-mediated signaling pathway; positive regulation of non-canonical NF-kappaB signal transduction; positive regulation of p38MAPK cascade; protein polyubiquitination; regulation of epithelial cell migration; regulation of protein autoubiquitination; regulation of protein K63-linked ubiquitination
Cellular component: cytoplasm; cytosol; protein-containing complex
Genetic constraint (gnomAD): Loss-of-function variants: 31 observed, 101.64 expected, observed/expected ratio (o/e) 0.31, 90% interval 0.23 to 0.41. The upper end of that interval is the gene's LOEUF score, 0.41, which puts it in group 1 of 6, group 1 being the genes least tolerant of losing a copy. Missense variants: 1,295 observed, 1,515.3 expected, observed/expected ratio (o/e) 0.85, 90% interval 0.82 to 0.89. Synonymous variants: 600 observed, 623.67 expected, observed/expected ratio (o/e) 0.96, 90% interval 0.9 to 1.03.
Homologues: Orthologues: chimpanzee SASH1 (99% identical), macaque SASH1 (97% identical), dog SASH1 (89% identical), pig SASH1 (88% identical), guinea pig SASH1 (87% identical), rat Sash1 (86% identical), mouse Sash1 (85% identical), rabbit SASH1 (85% identical), zebrafish sash1a (57% identical), tropical clawed frog sash1 (53% identical), zebrafish sash1b (44% identical). Paralogues in human: SASH3 (13% identical), SAMSN1 (13% identical).
Diseases named in the same sentence as SASH1 in open-access papers:
SASH1 is named in the same sentence as 72 diseases in open-access papers, as found by Europe PMC text mining. Sharing a sentence is not in itself a finding about the gene and the disease. The quoted sentences say what the papers report.
breast carcinoma (17 papers, 2006 to 2025). "SASH1 was originally described in 2003 and linked to potential tumor suppressor activity in breast cancer." (PMID 39942820, 2025). "Loss of heterozygosity (LOH) at RAD51 15q14-15 loci and 6q23-24 at SASH1 loci in breast cancer has been linked to poor outcomes." (PMID 30627325, 2018). "The SASH1 gene was originally thought to work as a tumour suppressor for breast cancer and colon cancers and has been demonstrated to have a crucial regulatory role in tumorigenesis." (PMID 34174894, 2021). "SASH1 was firstly identified as a potential tumor suppressor gene in breast cancer, which played a crucial role in tumorigenesis, development, invasion and metastasis." (PMID 32849825, 2020). "Our earlier work in breast cancer indicated that chloropyramine can induce cell death via a SASH1-dependent mechanism." (PMID 33122723, 2020). "Our previous data have shown that chloropyramine, a known competitive reversible H1-receptor antagonist (also known as an H1 inverse agonist), can increase SASH1 protein levels in breast cancer cells." (PMID 33122723, 2020). "SAM and SH3 domain containing 1 (SASH1) is a tumor suppressor whose expression is downregulated in breast cancer and CRC." (PMID 32456226, 2020). "SASH1 is shown to be downregulated in breast cancer and, when highly expressed, SASH1 can inhibit proliferation, invasion, and endothelial mesenchymal transition in other malignancies such as hepatocellular carcinoma and gastric cancer." (PMID 32230784, 2020). "In our study, the levels of p-PI3K/PI3K and p-AKT/AKT were significantly decreased by SASH1 overexpression, suggesting that SASH1 blocks the malignant biological behaviors of breast cancer cells through the inhibition of PI3K/AKT signaling pathway." (PMID 32670859, 2020). "The expression of SAM and SH3 domain-containing 1 (SASH1) was first reported to be significantly decreased in breast cancer samples by Zeller in 20031." (PMID 31138780, 2019). "We initially quantified SASH1 protein expression in eight breast cancer cell lines by immunoblot analysis." (PMID 27637080, 2016). "We found that the antihistamine chloropyramine induced SASH1-dependent cell death in a panel of breast cancer cell lines." (PMID 27637080, 2016). "In contrast SASH1 siRNA-transfected breast cancer cells exhibited reduced chloropyramine sensitivity." (PMID 27637080, 2016). "Consistent with the connectivity screen, chloropyramine induced SASH1 expression in seven of the eight breast cancer cell lines tested, and reduced the viability of six lines." (PMID 27637080, 2016). "The prognostic significance of SASH1 expression is less characterised in breast cancer compared with other malignancies, so we investigated this using two clinically-annotated tumour cohorts." (PMID 27637080, 2016). "We also analysed relapse-free survival in ER+ cases with high and low relative expression of SASH1 mRNA by meta-analysis of breast cancer gene expression data from the KM plotter database." (PMID 27637080, 2016). "Next, we analysed the relationships between SASH1 expression and breast cancer-specific survival by Kaplan-Meier analysis, separating the cohort into clinically-relevant subgroups." (PMID 27637080, 2016). "Pharmacologic induction of SASH1 by chloropyramine treatment of breast cancer warrants further preclinical and clinical investigation." (PMID 27637080, 2016). "We have focused on the gene SASH1 (SAM- and SH3-domain containing 1) that has previously been described as candidate tumour suppressor gene in breast cancer." (PMID 17088907, 2006). "SASH1 was mapped to chromosome 6q24.3, loss of heterozygosity (LOH) of this region (occurring in 30% of primary breast cancers) was associated with poor survival and increase in tumour size." (PMID 17088907, 2006).
breast carcinoma (continued). "In breast cancer tissues, a significant downregulation of SASH1 expression has been observed, whereas upregulation of SASH1 is able to block the proliferation and invasion of breast cancer cells through inhibition of the PI3K-Akt-mTOR (mammalian target of rapamycin) signaling route." (PMID 39942820, 2025). "The expression of SASH1 is inversely correlated with poor survival of patients with breast cancer." (PMID 32456226, 2020). "Based on these results, the malignant biological behaviors of breast cancer cells might be inhibited by SASH1 overexpression through the inhibition of PI3K/AKT signaling pathway." (PMID 32670859, 2020). "Ectopic SASH1 expression increased apoptosis in 7/8 breast cancer cell lines." (PMID 27637080, 2016). "Overall, the data suggest that SASH1 is prognostic in breast cancer and could have subtype-dependent effects on breast cancer progression." (PMID 27637080, 2016). "After validating the chloropyramine-mediated induction of SASH1 in breast cancer cell lines at the protein level, we investigated whether this treatment could mimic the effect of SASH1 over-expression on cell growth and survival." (PMID 27637080, 2016). "This study investigated whether increasing SASH1 expression could be a useful therapeutic strategy in breast cancer." (PMID 27637080, 2016). "The prognostic significance of SASH1 expression was also investigated in two breast cancer cohorts." (PMID 27637080, 2016). "This study demonstrated that chloropyramine increased SASH1 protein levels in breast cancer cells." (PMID 27637080, 2016). "Recent work has led to the prediction that SASH1 may function as a tumor suppressor and play a significant role in breast cancer and lung cancer." (PMID 19727444, 2009). "Indeed, frequent LOH at the SASH1 genomic locus 6q24–25 has been reported in primary breast cancer, and also in one study in primary colorectal tumours, with specific association with tumour invasion to the serosal fat." (PMID 17088907, 2006). "Consistent with this, we found that ectopic expression of SASH1 reduced breast cancer cell line viability, and so we hypothesised it could be involved in processes required for maintaining cancer cell viability in vivo, and that increasing its expression could be a novel treatment strategy." (PMID 27637080, 2016). "However, despite extensive sequencing efforts, Zeller and co-workers have not been able to demonstrate invalidating mutations in the second allele that would explain the lack of expression of SASH1 in breast cancer." (PMID 17088907, 2006). "Chloropyramine has previously been shown to have anti-tumour activity in breast cancer in part through modulation of FAK signalling, a pathway also regulated by SASH1." (PMID 27637080, 2016). "The gene SASH1 (SAM- and SH3-domain containing 1) has originally been identified as a candidate tumour suppressor gene in breast cancer." (PMID 17088907, 2006). "SAM and SH3 domain containing 1 (SASH1) is a signal adapter protein of the SLY family, a well-known tumor suppressor gene that shows decreased expression in various cancers such as breast cancer, colorectal cancer, non-small-cell lung cancer (NSCLC), gastric cancer, and cervical cancer." (PMID 37510314, 2023). "The mRNA levels of TGM2, SASH1, PARP9, STAT1 and ANXA1 were not significantly different between ER+ and ER--breast cancer tissues." (PMID 29416786, 2018).
colon carcinoma (10 papers, 2006 to 2025). "While CrkL knockout blocked SASH1 deficiency-induced EMT in HCT116 colon cancer cells, Crk/CrkL double knockout inhibited Src activation-induced EMT." (PMID 33801580, 2021). "In conclusion, we have demonstrated that downregulation of SASH1 expression in colon cancer is associated with metastasis and bad prognosis." (PMID 17088907, 2006). "SASH1 is believed to be a tumor suppressor in breast and colon cancer and has been shown to inhibit cell migration and enhance cell adhesion of epithelial cells." (PMID 28193179, 2017). "We have used quantitative real-time PCR to investigate the expression of SASH1 in tissue samples from 113 patients with colon carcinoma, and compared the expression with 15 normal colon tissue samples." (PMID 17088907, 2006). "Expression levels of SASH1 were strongly and significantly reduced in colon cancer of UICC stage II, III, and IV, as well as in liver metastases." (PMID 17088907, 2006). "Overall, 48 out of 113 primary colon tumours showed SASH1 expression that was at least 10-fold lower than the levels found in normal colon tissue." (PMID 17088907, 2006). "Here, we provide the first evidence that downregulation of SASH1 constitutes an independent prognostic parameter in colon cancer." (PMID 17088907, 2006). "In addition, two genes that either suppress (SASH1) or induce (MACC1) metastasis in colon cancer were included." (PMID 30340556, 2018). "Even though sporadic MSI-high colon cancer differs from the rare hereditary forms, it is tempting to speculate that there may be a connection between normal SASH1 expression in tumours and high MSI levels." (PMID 17088907, 2006). "SASH1, containing highly similar protein structure with SASH3, functions as a tumor suppressor to inhibit the development of many cancers, such as colon cancer, gastric cancer, BRCA, and cervical cancer." (PMID 35047378, 2021). "Moreover, in the colon cancer group, compared to those without liver metastasis, those with liver metastasis had much lower SASH1 expression." (PMID 26424902, 2015).
lung carcinoma (10 papers, 2009 to 2025). "SASH1 has previously been recognized as having a potential role in lung cancer susceptibility with the SASH1 gene located at a major lung cancer susceptibility locus on Chromosome 6q23-254,5." (PMID 33122723, 2020). "Among the predicted targets, SASH1 and DOCK4, which have been implicated in lung cancer prognosis, are recognized as oncogenes in LUAD." (PMID 40529490, 2025). "Overexpression of SASH1 inhibited proliferation and invasion in a human lung cancer cell line and suppressed TGF-β1-mediated epithelial-mesenchymal transition (EMT), migration, and invasion in a human gastric cancer cell line." (PMID 37510314, 2023). "Here, we assessed the use of chloropyramine as a chemical agent to increase SASH1 protein levels and induce tumour cell killing of lung cancer cells." (PMID 33122723, 2020). "Supporting this, modulation of SASH1 levels in a panel of lung cancer cell lines mediated changes in cellular proliferation and sensitivity to cisplatin." (PMID 33122723, 2020). "Agents that upregulate SASH1 are potential novel approaches to the management of lung cancer and warrant further preclinical and clinical studies of chloropyramine." (PMID 33122723, 2020). "As platinum-based chemotherapy is among the most utilised chemotherapeutic treatment strategies in lung cancer, we examined the impact of SASH1 depletion on the cellular sensitivity of NSCLC cell lines to cisplatin." (PMID 33122723, 2020). "The treatment of lung cancer cells with chloropyramine, a compound that increases SASH1 protein concentrations, reduced cellular proliferation and increased sensitivity to cisplatin in a SASH1-dependent manner." (PMID 33122723, 2020). "The correlation of SASH1 mRNA and protein was determined to have an R2 value of 0.7115 within a lung cancer cohort." (PMID 33122723, 2020). "Consistently, depletion of SASH1 from A549 lung cancer cells suppressed apoptosis, whereas the use of an alternative siRNA targeting SASH1 (GenePharma, Shanghai, China) also significantly suppressed apoptosis." (PMID 27831555, 2016). "SASH1 has been described as a tumour suppressor, with overexpression resulting in an increase in cell death in lung cancer, melanoma, osteosarcoma and glioma cell lines." (PMID 27637080, 2016). "Indeed, interrogating other KM Plotter cancer datasets we found strong associations between SASH1 mRNA expression and better overall survival in lung cancer but very poor outcome in gastric cancer (data not shown)." (PMID 27637080, 2016). "E xpression of the hub genes HBEGF, GJA4, DDR1, CD24, TBX2, GATA3, and SASH1 did not appear to be prognostic in lung cancer." (PMID 37324026, 2023). "Although only a moderate difference in SASH1 protein expression was observed between the non-cancerous cell line HBEC4 and the lung cancer cell lines in our study, 5/11 lung cancer cases from the Human Protein Atlas database have non-detectable SASH1 protein levels." (PMID 33122723, 2020).
colorectal cancer (9 papers, 2006 to 2025). A primary or metastatic malignant neoplasm that affects the colon or rectum. "Moreover, the increased invasion of SASH1-deficient colorectal cancer cells was completely counteracted by the removal of CrkL." (PMID 40362257, 2025). "It has been shown that SAM and SH3 domain-containing 1 (SASH1) is a putative tumor suppressor gene in lung, breast, thyroid and colorectal cancers." (PMID 35756681, 2022). "SAM and SH3 domain containing 1 (SASH1) was initially identified as a putative tumor suppressor gene, based on detection of significantly lower mRNA levels in lung, breast, thyroid and colorectal cancers compared to adjacent normal tissue." (PMID 33122723, 2020). "Compared to tumors from stage II colorectal cancer (n = 222), microsatellite instability was significantly less frequent, osteopontin expression was significantly increased, and SASH1 expression significantly decreased." (PMID 30340556, 2018). "SAM and SH3 domain containing 1 (SASH1) was initially identified as a putative tumour suppressor gene, based on detection of significantly lower mRNA levels in lung, thyroid and colorectal cancers compared to adjacent normal tissue." (PMID 27637080, 2016). "SASH1, which contains a Src-homology 3 domain, inhibited EMT by engaging with the oncoprotein CrkL in colorectal cancer cells." (PMID 40362257, 2025). "Colorectal cancer (CRC) cell lines HT29 and HCT116, incubated with siRNA for SASH1 mRNA in the presence of transportan and TP10, showed cellular uptake and a decreased SASH1 mRNA level." (PMID 34210007, 2021).